GBA1 (glucosylceramidase beta 1)
Diseases named in the same sentence as GBA1 in open-access papers (continued):
Sharing a sentence is not in itself a finding about the gene and the disease.
synucleinopathies (continued). "For example, many different GBA1 mutations are associated with α-synucleinopathies, including putative null alleles, and the molecular severity of a GBA1 allele correlates with the risk of developing an α-synucleinopathy in heterozygous carriers." (PMID 27019408, 2016). "Heterozygous GBA1 mutations are found in a high frequency in PD patients and thus are considered to be the most common genetic risk factor for synucleinopathies." (PMID 25946078, 2015). "Variants in GBA1 are common genetic risk factors for several synucleinopathies." (PMID 40667145, 2025). "Pathogenic variants in the GBA1 gene, which encodes the enzyme β-glucocerebrosidase, are well-established risk factors for α-synucleinopathies, including PD; however, their impact on the clinical spectrum of PD remains unclear." (PMID 40282414, 2025). "Moreover, heterozygous GBA1 variants represent the most prevalent genetic risk factor for alpha-synucleinopathies such as Parkinson’s Disease (PD) and Dementia with Lewy Bodies (DLB)." (PMID 39795868, 2024). "GBA1 mutations have varying degrees of impact on both GD and GBA1‐associated synucleinopathies." (PMID 38641924, 2024). "While most studies focus on the role of GBA1 in promoting synucleinopathy, neuroinflammation may be a key pathogenic alteration caused by GBA1 loss." (PMID 37745332, 2024). "This knowledge might aid in identifying individual risk factors and potential biomarkers for GBA1‐related PD and associated synucleinopathies." (PMID 38641924, 2024). "Hence, GBA1 variants prevail as an intriguing subject to investigate in the context of α-synucleinopathies." (PMID 36768367, 2023). "Here, we discuss some of the potential interactions between α-synuclein and GCase and show how GBA1 mutations may impact the course of the most prevalent α-synucleinopathies." (PMID 36768367, 2023). "The precise mechanism by which GBA1 variants increase the risk for developing alpha synucleinopathy in PD remains unknown." (PMID 33402667, 2021). "For instance, additional risk factors may influence cellular alpha-synuclein homeostasis concurrently with GBA1 variants in an epistatic manner, thereby modifying the risk of alpha synucleinopathy attributed to GBA variants and hence their penetrance." (PMID 33402667, 2021). "While the genetic link between GBA1 mutations and synucleinopathies such as PD and LBD is the strongest argument linking GCase deficit with the appearance of synucleinopathies, the ultimate basis for this association has remained elusive, with very little experimental evidence to date." (PMID 28835999, 2018). "However, heterozygous mutations in GBA1 have been associated with a significantly heightened risk of developing synucleinopathies." (PMID 27126635, 2016). "Therefore, strategies aimed to maintain GBA1 enzyme activity could be employed to develop an effective novel therapy for GBA1 linked-PD and related α-synucleinopathies." (PMID 29703245, 2018). "Lipidomic analyses demonstrated that EVs from GBA1 carriers with synucleinopathies were loaded with ceramides, which is in agreement with our data." (PMID 41009720, 2025). "The GBA1–GCase axis provides a compelling mechanistic link between lysosomal lipid metabolism and α-synucleinopathies and holds promise for stratified therapeutic approaches." (PMID 41465169, 2025). "Preclinical data support that in GBA1 mutant mouse models or synucleinopathy models, viral delivery of GBA1 increased GCase activity, decreased GlcCer/GlcSph, reduced α-syn aggregation and ameliorated behavioural/neurodegenerative changes." (PMID 41465169, 2025). "Experimental GBA1 gene therapy in an α-synucleinopathy mouse model increased brain GBA1 activity and prevented α-synuclein aggregation." (PMID 37947642, 2023). "GBA1 mutations constitute one of the highest risk factors for developing PD and DLB, which are the most prevalent α-synucleinopathies." (PMID 36768367, 2023).
synucleinopathies (continued). "This review concentrates on GBA1 as the most important gene in the pathogenesis of α-synucleinopathies." (PMID 36768367, 2023). "Damaging coding variants in GBA1 are a genetic risk factor for rapid eye movement sleep behavior disorder (RBD), which is a known early feature of synucleinopathies." (PMID 38076854, 2023). "In a GBA1-mouse model recently shown to mimic prodromal stages of α-synucleinopathy, we now demonstrate striking REM and NREM electroencephalographic sleep abnormalities accompanied by distinct structural changes in the more widespread sleep neurocircuitry." (PMID 35562385, 2022). "Mutations in GBA1, the gene encoding GBA, are linked to an increased risk of PD, LBD, and other synucleinopathies." (PMID 36421678, 2022). "Concerning PD, the huge knowledge on GBA1 catalytic functions places the focus on the metabolism of steryl glycosides, molecules that are known to trigger a PD-related synucleinopathy in rodents." (PMID 31277513, 2019). "Here, we show that GBA1 enzyme activity plays a significant role in the hA53T α-synuclein induced α-synucleinopathy." (PMID 29703245, 2018). "Ongoing early-phase clinical trials and vector optimization efforts will be crucial in establishing whether AAV-based GBA1 gene therapy can provide a durable and disease-modifying treatment for PD and related synucleinopathies." (PMID 41465169, 2025). "In the neuronal in vitro cell system GCase supplementation can revert α-synuclein aggregation induced by PFFs, suggesting that GCase expression alone can be effective to treat α-synucleinopathies independent of a GBA1 mutation status." (PMID 40333681, 2025). "Understanding the mechanistic links between GBA1 and synucleinopathy has driven development of therapeutic strategies centred on GCase augmentation, substrate reduction, chaperone therapy, gene therapy, and modification of downstream pathways (autophagy, lysosomes, lipids)." (PMID 41465169, 2025). "Beyond known PD genes GBA1 and LRRK2, rare variants AD genes (CD33, CR1 and PSEN2) and Aβ toxicity modifiers involved in RhoA/actin cytoskeleton regulation (ARGHEF1, ARHGEF28, MICAL3, PASK, PKN2, PSEN2) were shared risk factors across synucleinopathies." (PMID 38496508, 2024). "While most research has primarily focused on GBA1’s role in promoting synucleinopathy, emerging evidence suggests that neuroinflammation may be a key pathogenic alteration caused by GBA1 deficiency." (PMID 37745332, 2024). "Mutations in the GBA gene (GBA1) result in an increased risk of PD and other synucleinopathies." (PMID 38397410, 2024). "At the same time, the role of α-SNCA in the etiopathogenesis of PD was well characterized, but there was no clear link on how GBA1 defects can be a risk factor for synucleinopathies." (PMID 37189391, 2023). "The mechanisms by which GBA1 mutations increase the risk of synucleinopathies are not fully understood." (PMID 35614915, 2022). "Similarly, we believe that these findings also advance the relevance of the GBA1 mice as a valuable model for future exploration of neurostructural and physiological targets in iRBD, and its links with other α-synucleinopathies." (PMID 35562385, 2022). "Haploinsufficiency of GBA1, which causes reduced activity of glucocerebrosidase (GCase), is associated clinically with a significantly increased risk of PD and LBD, and with faster rate of cognitive decline in α-synucleinopathies, including LBD and PD." (PMID 31649605, 2019). "Here, we hypothesized that there may be increased MUFAs in a nonprimary α-synucleinopathy, resulting from mutations associated with GBA1-PD." (PMID 40459948, 2025). "It has been proposed that GBA1 variants might contribute to the accumulation of α-synuclein in patients with PD, while the role of GBA variants in the pathogenesis of MSA, which is also an α-synucleinopathy, remains unclear." (PMID 39020124, 2024).
synucleinopathies (continued). "In addition, GCase has been shown to be important in regulating the turnover of aSyn—presumably via the autophagy-lysosome system—with mutant GBA1 implicated in exacerbating synucleinopathy in some, but not all, models." (PMID 34106956, 2021). "The role of GBA1 mutations in the pathogenesis of synucleinopathies is not fully understood, but experimental data suggest that there may be a direct relationship between the level of glucocerebrosidase activity and α-synuclein proteostasis." (PMID 27126635, 2016). "Further, the same sponsor announces the development of an approach combining GBA1 gene transfer and SCNA knockdown for treatment of synucleinopathies in general." (PMID 33324928, 2020). "Further studies are needed to explore whether GBA1 rs3115534 affects the rate of phenoconversion from RBD to PD and other synucleinopathies such as DLB and MSA." (PMID 38076854, 2023). "Here, we have implemented a gene therapy strategy to enhance GCase activity in mice and nonhuman primate (NHP) models of PD-like synucleinopathy by taking advantage of the intraparenchymal focused delivery into the substantia nigra pars compacta (SNpc) of rAAVs coding for the GBA1 gene." (PMID 34062940, 2021). "Importantly, even heterozygous carriers of GBA1 mutations—who typically do not manifest GD—have elevated risk for PD and DLB, which indicates that partial GCase deficiency (or dysfunction) in the brain is sufficient to modify risk of synucleinopathy." (PMID 41465169, 2025).
Cognitive impairment (67 papers, 2012 to 2025). Abnormal cognition is characterized by deficits in thinking, reasoning, or remembering. "Between GBA1-associated and sporadic PD, pathways related to cognitive impairment, memory deficits, and hormone imbalance were enriched, highlighting common neurodegenerative and endocrine-related dysfunctions in both PD subtypes." (PMID 41301891, 2025). "Patients with severe and complex GBA1-PD exhibited a significant symptom burden, with an elevated risk of hallucinations and cognitive impairment." (PMID 39766872, 2024). "The hallmark conclusion is that cognitive impairment which stands as a ‘clinical signature’ of GBA1-PD, seems to have its neuroimaging correlation in greater burden of cortical region in these patients compared to iPD." (PMID 36768367, 2023). "On the contrary to other PD symptoms, the degree of cognitive impairment is correlated with the severity of GBA1 mutation and GCase activity." (PMID 36768367, 2023). "The presence of GBA1 mutations has been also shown to affect the clinical phenotype of PD with a more rapid disease progression and cognitive impairment." (PMID 33036336, 2020). "A more recent study extended this notion demonstrating that psychiatric symptoms, cognitive impairment, and olfactory deficiency are more pronounced in PD patients carrying severe GBA1 mutations." (PMID 32372943, 2020). "The type of PD associated with GBA1 mutations (PD‐GBA1) is almost identical to idiopathic PD, except for a slightly younger age of onset and a tendency to more cognitive impairment." (PMID 26860875, 2016). "The homozygous GBA1 L444P mutation is described to cause a severe form of GD with greatly decreased GCase levels and has been identified as PD risk gene with 5.6-fold increased risk of cognitive impairments." (PMID 40333681, 2025). "Our findings show the risk of cognitive impairment is highest in GBA1 p.N409S carriers." (PMID 40926580, 2025). "Finally, the same group compared 35 Greek GBA1 carriers with 35 genetically unidentified PD patients and revealed more cognitive deficits and a higher prevalence of bilateral motor symptoms onset in carriers of GBA1 variants." (PMID 39766872, 2024). "Overall, GBA1 pathogenic variants have been linked to more severe motor and cognitive impairment." (PMID 39766872, 2024). "The degree of cognitive impairment is correlated with the severity of GBA1 mutations." (PMID 35932311, 2022). "In previous studies, GBA1 mutation was associated with early-onset, the relatively symmetrical onset of limb symptoms, and faster motor and cognitive impairment progression in PD patients; however, the association between different GBA mutation subtypes are less studied." (PMID 36590455, 2022). "Interestingly, early cognitive impairment has been associated with GBA1-related PD, postural and action tremor has been reported in asymptomatic carriers of LRRK2 mutations, and PD patients with SNCA mutations display early dementia." (PMID 33036336, 2020). "Both patients with GD and GBA1 carriers were shown to have impaired olfaction and some cognitive impairment compared to healthy controls." (PMID 40508068, 2025). "Beta-glucocerebrosidase (GBA1) is a membrane-bound lysosomal enzyme, and the accumulation of its substrates in neurons has been associated with cognitive impairments, motor and coordination deficits, and psychiatric disorders." (PMID 40955304, 2025). "Patients with GBA1 mutations (GBA-PD) exhibit earlier age of onset and faster disease progression with more severe cognitive impairments, postural instability and gait problems." (PMID 37748026, 2024). "Specifically, the most common genetic risk factors for PD, mutations in GBA1, were reported to be associated with a higher frequency of FOG and cognitive impairment in PD, as well as a more severe disease progression rate in the longitudinal follow-up." (PMID 39463818, 2024).
Cognitive impairment (continued). "Progression to mild cognitive impairment was worse among the combined GBA1 group (OR, 4.2; 95% CI: 1.1–16.6; P < 0.05), heterozygous (OR, 2.6; 95% CI: 1.6–11.4; P < 0.05), and biallelic group (OR, 8.2; 95% CI: 1.6–41.0; P < 0.05)." (PMID 31251436, 2019). "Because GBA1 mutations are frequently associated with cognitive impairment, and the phenotypes of the GBA1ΔTT homozygotes are similar to those of previously characterized Drosophila models of neurological dysfunction, we tested whether GBA1ΔTT homozygotes also exhibited a cognitive defect." (PMID 27019408, 2016). "Furthermore, long-term assessment and analyses showed a worse trajectory of cognitive impairment in GBA1- PD patients." (PMID 39766872, 2024). "Normalising lipid levels in a GBA1-PD mouse model improved cognitive deficits." (PMID 35932311, 2022). "Cognitive impairment was worse at all time points among the combined group of GBA1 carriers." (PMID 31251436, 2019). "GBA1 patients showed more severe symptoms and a higher burden of motor and non-motor complications compared to negative patients (dyskinesias OR 3, sleep disturbances OR 2.8, cognitive deficits OR 3.6; p < 0.05), with greater autonomic dysfunction (COMPASS-31 score 34.1 vs 20.2, p 0.03)." (PMID 39034353, 2025). "Not all GBA1 variants are equal: some (e.g., L444P) or complex alleles are typically associated with markedly reduced GCase activity, leading to earlier disease onset, faster progression, and a higher prevalence of cognitive impairment or DLB." (PMID 41465169, 2025). "Clinically, patients with PD with GBA1 variants show an earlier age at onset, more rapid disease progression, and higher rates of nonmotor symptoms, such as rapid eye movement sleep behavior disorder (RBD) and cognitive impairment, compared with those with non-GBA1–associated PD." (PMID 38329128, 2024). "Clinically, GBA1-associated PD (GBA1-PD) mirrors idiopathic PD (iPD), albeit significant differences include an earlier age of disease onset, greater frequency of non-motor symptoms (NMSs) and cognitive impairment." (PMID 35932311, 2022). "GBA1-PD patients present with a higher prevalence of non-motor symptoms including cognitive impairment and dementia, rapid eye movement (REM) sleep behavioral disorder (RBD) and autonomic failure." (PMID 40508068, 2025). "In recent studies, the most beneficial treatment on the motor symptoms was evaluated with deep brain stimulation (DBS) in a cohort of GBA1-PD patients compared to iPD, albeit cognitive impairment and non-motor symptoms did not improve." (PMID 36768367, 2023). "Patients harboring GBA1 variants have an approximately five years earlier age of DLB onset, increased hallucinations, worse REM sleep behavior disorder (RBD) symptoms, more severe motor and cognitive impairment and rapid symptom progression compared to non-carriers." (PMID 36768367, 2023).
depression (22 papers, 2018 to 2025). "It is assumed that depression in GBA1-PD is associated with microstructural damages in the limbic system." (PMID 36768367, 2023). "In addition, we found that depression was likelier to occur in PD patients with GBA1 variants." (PMID 37658046, 2023). "The association between genetic status (GBA1 and APOE ε4 carrier status) and the four Neuropsychiatric dimensions (depression, anxiety, adult stress-adversity, ASRB) was assessed using mixed-effects models." (PMID 41326418, 2025). "Compared to iPD, we observed that only severe GBA1-PD patients had a distinctive, more several clinical profile, characterised by worse depression, hyposmia, cognitive dysfunction, and possibly constipation." (PMID 41034226, 2025). "GBA1-PD patients presented with more severe depression (β = 2.3, p = 0.0026), olfactory dysfunction (β = −2.03, p = 0.0054), and motor complications (β = 0.8, p = 0.0399)." (PMID 41034226, 2025). "In this study, we investigated the expression of the PD-related genes SNCA, GBA1, and UGCG in human blood cells of MDD patients and matched controls and their association with the severity of depression, anxiety, and PD-related laboratory parameters." (PMID 38542193, 2024). "It has been found that GBA1-PD had a greater prevalence of depression (33.3%) versus iPD (13.2%) (p < 0.05)." (PMID 36768367, 2023). "The newest study has reported that GBA1-PD patients with depression showed statistically valuable decreased fractional anisotropy or increased mean diffusivity in the specific brain regions compared with matched iPD patients with depression." (PMID 36768367, 2023). "The hypokinetic/rigid picture seems to be in line with what is reported in the literature about PRKN and GBA1 mutations, while the important anxiety–depressive syndrome follows the non-motor symptomatology often associated with GBA1." (PMID 40141040, 2025). "Furthermore, GBA1 variants carriers within the LOPD group displayed a higher occurrence of olfactory loss, depression, pRBD and constipation." (PMID 37658046, 2023). "Patients with GBA1 variants, compared to those without GBA1 variants, exhibited an earlier age at onset, and higher risk of pRBD, olfactory dysfunction, depression, and autonomic dysfunction." (PMID 37658046, 2023). "Patients with GBA1 variants exhibited an earlier onset age and higher risk of probable rapid-eye-movement sleep behavior disorder, olfactory dysfunction, depression, and autonomic dysfunction than patients without GBA1 variants." (PMID 37658046, 2023). "With respect to GBA1, there appears to be an increased risk of neuropsychiatric comorbidities, such as anxiety and depression, in men but not women with GBA1 mutations, suggesting a sex–genotype interplay in PD symptom manifestation." (PMID 32560161, 2020). "In addition, patients with non-synonymous GBA1 variants displayed higher rates of constipation and depression than non-carriers." (PMID 37658046, 2023). "We identified significantly elevated expression levels of all three genes in individuals with depression: SNCA (+27%, p = 0.036), GBA1 (+56%, p = 0.014), and UGCG (+75%, p = 0.0002)." (PMID 38542193, 2024). "LRRK2 p.G2019S PD reported less nocturia and orthostatic hypotension than GBA1 p.N409S PD and noncarriers with PD, and less erectile dysfunction and depression relative to noncarriers with PD." (PMID 40926580, 2025). "Compared with iPD, worse depression was the only differing feature found in mild GBA1-PD (β = 3.5, p = 0.0139), whereas no differing features were observed between iPD and risk GBA1-PD." (PMID 41034226, 2025). "Therefore, akin to depression severity scores, we examined the correlation between SNCA, GBA1, and UGCG expressions and anxiety scores." (PMID 38542193, 2024).